MIA2 (MIA SH3 domain ER export factor 2)
Description:
Plays a role in the transport of cargos that are too large to fit into COPII-coated vesicles and require specific mechanisms to be incorporated into membrane-bound carriers and exported from the endoplasmic reticulum. Plays a role in the secretion of lipoproteins, pre-chylomicrons and pre-VLDLs, by participating in their export from the endoplasmic reticulum. Thereby, may play a role in cholesterol and triglyceride homeostasis (By similarity). Required for collagen VII (COL7A1) secretion by loading COL7A1 into transport carriers and recruiting PREB/SEC12 at the endoplasmic reticulum exit sites.
Synonyms: CTAGE5; MEA6; MGEA11; MGEA6; FLJ22404; TALI; cTAGE-5A; cTAGE-5B; cTAGE-5C; cTAGE-5D; MGEA
Tractability: Antibody: UniProt predicts a signal peptide or a membrane-spanning region. PROTAC: ubiquitination databases record sites on it.
Gene: Protein-coding gene on chromosome 14 (39,230,231 to 39,388,513, forward strand). Ensembl gene ENSG00000150527.
Subcellular location: Endoplasmic reticulum membrane
Subcellular location (Human Protein Atlas): Endoplasmic reticulum
Pathways (Reactome):
Vesicle-mediated transport: Cargo concentration in the ER
Gene Ontology:
Molecular function: protein binding
Biological process: endoplasmic reticulum to Golgi vesicle-mediated transport; protein secretion; vesicle cargo loading
Cellular component: endoplasmic reticulum; endoplasmic reticulum exit site; endoplasmic reticulum membrane; membrane
Genetic constraint (gnomAD): Loss-of-function variants: 66 observed, 92.73 expected, observed/expected ratio (o/e) 0.71, 90% interval 0.58 to 0.87. The upper end of that interval is the gene's LOEUF score, 0.87, which puts it in group 3 of 6, group 1 being the genes least tolerant of losing a copy. Missense variants: 1,150 observed, 1,102 expected, observed/expected ratio (o/e) 1.04, 90% interval 0.99 to 1.1. Synonymous variants: 382 observed, 375.13 expected, observed/expected ratio (o/e) 1.02, 90% interval 0.94 to 1.11.
Homologues: Orthologues: chimpanzee MIA2 (99% identical), macaque MIA2 (94% identical), dog MIA2 (80% identical), mouse Mia2 (68% identical), rat Mia2 (67% identical), Drosophila melanogaster Tango1 (18% identical). Paralogues in human: CTAGE1 (47% identical), CTAGE8 (46% identical), CTAGE9 (46% identical), CTAGE15 (45% identical), CTAGE4 (45% identical), CTAGE6 (45% identical), MIA3 (25% identical), SPZ1 (5% identical), MIA (3% identical), OTOR (3% identical).
Diseases named in the same sentence as MIA2 in open-access papers:
MIA2 is named in the same sentence as 35 diseases in open-access papers, as found by Europe PMC text mining. Sharing a sentence is not in itself a finding about the gene and the disease. The quoted sentences say what the papers report.
hepatocellular carcinoma (7 papers, 2016 to 2023). A malignant tumor that arises from hepatocytes. "Treatment with recombinant MIA2 inhibited proliferation and invasion of hepatocellular carcinoma cells in vitro and in vivo." (PMID 34211824, 2021). "Although corresponding to tumor suppressive properties in hepatocellular carcinoma, MIA2 exhibits protumoral properties in oral squamous cell carcinoma, demonstrating increases in invasion, survival, and angiogenesis." (PMID 29156765, 2017). "In the case of hepatocellular carcinoma, MIA2 expression inhibits tumor proliferation." (PMID 34441956, 2021). "MIA2 regulates the COPII assembly and collagen secretion, while its depletion in hepatoma cells leads to the accumulation of lipid droplets." (PMID 36604669, 2023). "Decreased expression of genes, such as TNFRSF10B, MIA2, and BBC3, are answerable for the progression of various cancers, such as lung cancer, hepatocellular carcinoma, head, and neck cancer, but low expression of these genes may be responsible for the development of BRCA." (PMID 31311202, 2019).
melanoma (4 papers, 2015 to 2024). A malignant, usually aggressive tumor composed of atypical, neoplastic melanocytes. "MIA and MIA2 are expressed not only in malignant melanoma but also within various malignant tumors, and their expression appears to increase with malignant transformation." (PMID 34441956, 2021). "Melanoma inhibitory activity 2 (MIA2), a protein facilitating protein secretion, is an HNF1A target." (PMID 25657029, 2015). "Melanoma inhibitory activity (MIA) and MIA2 are other receptors participating in tumour growth and invasion." (PMID 38540190, 2024). "Melanoma inhibitory activity (MIA) and MIA2 are involved in tumor growth, invasion, and lymph node metastasis in various malignancies." (PMID 34441956, 2021). "The melanoma inhibitory activity (MIA) gene family includes MIA, MIA2, Transport and Golgi organization protein 1 (TANGO), and otoraplin (OTOR)." (PMID 27145272, 2016). "Melanoma inhibitory activity (MIA) gene family members include MIA, MIA2, and Transport and Golgi organization protein 1 (TANGO)." (PMID 27145272, 2016).
pancreatic cancer (3 papers, 2015 to 2024). "Taken together, we identified a common germline variant of MIA2I141M that is associated with a secretory defect of the MIA2 protein in pancreatic cancer cells." (PMID 25657029, 2015). "HNF-1A induced expression of MIA2 has also been implicated in pancreatic cancer." (PMID 29156765, 2017). "Since these data in PDAC strongly suggested that the secretion-associated MIA2 polymorphisms were associated with the clinical response to adjuvant chemotherapy, we sought to determine whether this was reflected in pancreatic cancer cell lines in vitro." (PMID 25657029, 2015). "It is expressed in several cancers, including pancreatic cancer, and breast cancer, suggesting that MIA2 may be involved in EC carcinogenesis." (PMID 38902713, 2024). "We then tested HNF1A and MIA2 expression in seven pancreatic cancer cell lines, out of which two (Aspc-1 and Colo-357) expressed both the HNF1A and MIA2 protein." (PMID 25657029, 2015).
cervical cancer (2 papers, 2016 to 2021). A primary or metastatic malignant neoplasm involving the cervix. "In pancreatic, esophageal, lung, and cervical cancers, however, MIA2 expression is associated with tumor progression." (PMID 34441956, 2021). "Furthermore, MIA (P < 0.0001), MIA2 (P = 0.0144), and TANGO expression (P = 0.0151) were associated with a poor prognosis among patients with cervical cancer." (PMID 27145272, 2016). "Non-tumor cervical mucosal samples had negative or very weak MIA gene family expression, whereas 34.1% (43/126), 31% (39/126), and 30.2% (38/126) of cervical cancer cases exhibited cytoplasmic MIA, MIA2, and TANGO staining, respectively." (PMID 27145272, 2016).
oral squamous cell carcinoma (2 papers, 2017 to 2023). "Kurihara etc., claimed that MIA2 could regulate the infiltration of lymphocytes via a variety of integrins and subtypes of mitogen-activated protein kinase in oral squamous cell carcinoma." (PMID 37730669, 2023).
epithelial dysplasia (1 paper, 2021). "MIA and MIA2 may therefore be novel IHC markers that enable discrimination between normal tissue and epithelial dysplasia." (PMID 34441956, 2021). "The expression of MIA and MIA2 was analyzed immunohistochemically in 100 specimens (10 specimens with normal oral mucosa (NOM) and 30 specimens each with low-grade epithelial dysplasia (LED), high-grade epithelial dysplasia (HED), and OSCC)." (PMID 34441956, 2021).
cancer (15 papers, 2014 to 2024). A tumor composed of atypical neoplastic, often pleomorphic cells that invade other tissues. "MIA2 expression is also associated with local expansion, nodal metastasis, and inhibited host anti-cancer immunity and apoptosis in OSCC." (PMID 27145272, 2016). "The low expression of MIA2 may result in the accumulation of VLDLs which was reported to be a risk factor for the development of cancer." (PMID 34211824, 2021). "High expression of CERCAM, HS6ST2, ONECUT2, SOX12 and TMEM132A and low expression of MIA2 related to poor outcomes for progression-free survival and cancer-specific survival." (PMID 35954418, 2022). "Since an exocrine-like subtype of PDAC has recently been identified and because HNF1A has been shown to be a novel cancer risk gene of PDAC32, it is likely that the HNFA/MIA2 secretory axis is active in PDACs." (PMID 25657029, 2015). "Since MIA2 is a secreted protein and is itself involved in protein secretion, MIA2 levels were analyzed in cancer cell supernatants by ELISA." (PMID 25657029, 2015). "Identifying changes in MIA and MIA2 expression via the immunohistochemical (IHC) examination of oral lesions related to cancer could contribute to the prevention of oral cancers." (PMID 34441956, 2021). "MALAT1 has been found to promote cell proliferation and migration of cancer cells by regulating the expression of genes promoting metastases, e.g., RASSF6, HNF4G, CA2, ROBO1, MIA2." (PMID 35887000, 2022). "The expression of MIA and MIA2 was only rarely observed in the keratinized layer in OED specimens, but a more pronounced expression was observed in the cancer pearl of OSCC." (PMID 34441956, 2021). "In this way, MALAT1 influences proliferation, invasion and migration of cancer cells through regulation of multitudinous known downstream genes, including several metastasis-related genes (CCT4/CTHRC1/ROBO1/MIA2) and cell cycle control genes (p21/p27/B-MYB)." (PMID 31792655, 2020). "Then, OED patients with MIA and MIA2 expression need to be the follow-up to clarify whether OED patients expressing MIA and MIA2 develop cancer at a higher rate." (PMID 34441956, 2021). "However, we observed that both PDAC cancer cells widely expressed HNF1A and MIA2 and some cancers even expressed them at a very high level." (PMID 25657029, 2015).
tumor (15 papers, 2015 to 2024). "MIA and MIA2 have been reported to be associated with cell migration, tumor invasion, and lymph node metastasis in OSCC, however, the role of MIA and MIA2 in OED is the subject of future research." (PMID 34441956, 2021). "Furthermore, when MIA2 is co-expressed with MIA, the overlap of integrin-mediated MIA- and MIA2-associated signaling further promotes tumor progression." (PMID 34441956, 2021). "Loss of MIA2 expression significantly correlated with advanced tumor stages." (PMID 34211824, 2021). "MIA2 (melanoma inhibitory activity 2) has been found in several malignancies and can act as a tumor suppressor or as a proto-oncogene depending on the receptor-related signaling differences." (PMID 35954418, 2022). "MIA2 is induced in liver fibrosis or cirrhosis by activating transforming growth factor-beta (TGF-β) signaling and serves as a tumor suppressor in liver cancers following the loss of hepatocyte nuclear factor-1 (HNF-1) expression." (PMID 27145272, 2016). "On the other hand, MIA2 expression correlated significantly with the clinical stage (P = 0.0026), local tumor cell progression (T classification; P = 0.0076), and nodal metastasis (P = 0.0069)." (PMID 27145272, 2016). "No obvious correlations were identified between the level of MIA and TANGO expression and tumor histological type; in contrast, the MIA2 expression levels increased from CIN3 (1/15, 6.7%) to invasive SCC (38/111, 34.2%; P = 0.0361)." (PMID 27145272, 2016). "Previously, the HNF1A/MIA2 secretory axis has been demonstrated to have a tumor suppressor function in HCC13." (PMID 25657029, 2015). "Several reports have revealed that MIA2 and TANGO can act as tumor suppressors; it is therefore interesting that according to our current results and previous findings, MIA2 and TANGO might behave as proto-oncogenes in SCCs of the esophagus, lung, and cervix." (PMID 27145272, 2016). "Cox regression analyses were performed to identify independent clinical prognostic parameters to construct a combined nomogram which includes the expression of CERCAM, MIA2, HS6ST2, ONECUT2, SOX12, TMEM132A, pT stage, tumor size and ISUP grade." (PMID 35954418, 2022). "Firstly, the underlying mechanism of the 6 identified PGRs, especially CITED2, EXOC6B, MIA2, and TRPV4, in OV progression and tumor immune microenvironment remained largely unknown, which needs stepwise investigation." (PMID 37730669, 2023). "MIA and MIA2 are also frequently expressed in OSCC, in which both promote tumor progression." (PMID 34441956, 2021).
MIA2 also shares sentences with these, for which no sentence is quoted: cutaneous T-cell lymphoma (2 papers); Glucose intolerance (2); lung carcinoma (2); movement disorder (2); adenocarcinoma (1); Anxiety (1); Blindness (1); breast carcinoma (1); cervical intraepithelial neoplasia (1); colon cancer (1); colonic adenocarcinoma (1); endometrial endometrioid adenocarcinoma (1); Fahr’s disease (1); glaucoma (1); head and neck cancer (1); hyperlipidemia (1); Impaired glucose tolerance (1); meningioma (1); Obesity (1); Optic neuropathy (1); ovarian serous adenocarcinoma (1); pancreatic adenocarcinoma (1); prostate carcinoma (1); prostate tumor (1); renal cell carcinoma (1); scleroderma (1); small cell carcinoma (1).